JOSD1 (Josephin domain containing 1)
Description:
Deubiquitinates monoubiquitinated probes (in vitro). When ubiquitinated, cleaves 'Lys-63'-linked and 'Lys-48'-linked poly-ubiquitin chains (in vitro), hence may act as a deubiquitinating enzyme. May increase macropinocytosis and suppress clathrin- and caveolae-mediated endocytosis. May enhance membrane dynamics and cell motility independently of its catalytic activity.
Synonyms: KIAA0063; dJ508I15.2
Tractability: Antibody: UniProt places it where antibodies can reach, with high confidence; its Gene Ontology location is reachable by antibodies, with medium confidence. PROTAC: UniProt records ubiquitination sites on it; ubiquitination databases record sites on it.
Target class: Enzyme; Hydrolase
Gene: Protein-coding gene on chromosome 22 (38,685,543 to 38,701,556, reverse strand). Ensembl gene ENSG00000100221.
Subcellular location: Cell membrane; Cytoplasm
Subcellular location (Human Protein Atlas): Cytosol; Vesicles
Pathways (Reactome):
Metabolism of proteins: Josephin domain DUBs
Gene Ontology:
Molecular function: protein binding; cysteine-type deubiquitinase activity; deubiquitinase activity
Biological process: protein deubiquitination
Cellular component: cytosol; membrane; cytoplasm; plasma membrane
Genetic constraint (gnomAD): Loss-of-function variants: 8 observed, 21.88 expected, observed/expected ratio (o/e) 0.37, 90% interval 0.21 to 0.66. The upper end of that interval is the gene's LOEUF score, 0.66, which puts it in group 2 of 6, group 1 being the genes least tolerant of losing a copy. Missense variants: 164 observed, 235.41 expected, observed/expected ratio (o/e) 0.7, 90% interval 0.61 to 0.79. Synonymous variants: 101 observed, 87.72 expected, observed/expected ratio (o/e) 1.15, 90% interval 0.98 to 1.36.
Homologues: Orthologues: chimpanzee JOSD1 (100% identical), macaque JOSD1 (100% identical), guinea pig JOSD1 (99% identical), pig JOSD1 (99% identical), dog JOSD1 (98% identical), mouse Josd1 (97% identical), rat Josd1 (97% identical), tropical clawed frog josd1 (75% identical), zebrafish josd1 (73% identical), Drosophila melanogaster Josd (40% identical), Caenorhabditis elegans josd-1 (33% identical). Paralogues in human: JOSD2 (50% identical).